NR2F1 (nuclear receptor subfamily 2 group F member 1)
Diseases named in the same sentence as NR2F1 in open-access papers (continued):
Sharing a sentence is not in itself a finding about the gene and the disease.
optic neuropathies (4 papers, 2019 to 2025). "This study demonstrates that the optic neuropathy caused by pathogenic NR2F1 variants is of early neurodevelopmental origin, with limited evidence of progression in later life." (PMID 34466801, 2021). "There are indications that NR2F1‐associated optic neuropathy leading to visual impairment is not progressive." (PMID 39972940, 2025). "Several of these genes, such as WFS1, SPG7, and NR2F1, are common causes of hereditary optic neuropathies and none of them has been previously associated with alcohol susceptibility, to the best of our knowledge." (PMID 38796496, 2024). "A recent study evaluating the NR2F1‐associated visual impairment could not find any evidence for progression but suggested the optic neuropathy to be congenital and stable." (PMID 39972940, 2025). "The findings suggest a neurodevelopmental basis for the observed visual impairment associated with NR2F1 variants, rather than the progressive RGC loss described in classical inherited optic neuropathies." (PMID 34466801, 2021). "First, Nr2f1 heterozygous mice, analogous to NR2F1 haploinsufficient patients, recapitulate important features of BBSOA patients, such as OD malformations and ON atrophy, and could serve as a model to study the pathogenesis of optic neuropathies and visual impairments." (PMID 31318166, 2019).
squamous carcinoma (4 papers, 2012 to 2022). "We have previously shown that both BHLHE41 and NR2F1 are required for or associated with dormancy of squamous carcinoma cells." (PMID 22530051, 2012). "Administration of NR2F1 agonist to the primary squamous cell carcinoma of the head and neck induced tumor dormancy and suppressed metastasis." (PMID 35740627, 2022). "In contrast, in a PDX model of squamous carcinoma, NR2F1 was upregulated in the DTCs that entered spontaneous dormancy, and additional results suggested that NR2F1 may pinpoint dormant DTCs in different cancer types." (PMID 30322396, 2018). "Nuclear receptor subfamily 2 group F member 1 (NR2F1) is an established biomarker of tumor dormancy that promotes quiescence of various types of cancer cells, including breast, prostate, and squamous cell carcinoma of the head and neck." (PMID 35740627, 2022).
autism (3 papers, 2019 to 2022). Persistent deficits in social interaction and communication and interaction as well as a markedly restricted repertoire of activity and interest as well as repetitive patterns of behavior. "Furthermore, we show that one of these lncRNAs, lnc-NR2F1 participates in neuronal maturation programs in vitro by regulating the expression of a network of genes previously linked to human autism." (PMID 30628890, 2019). "We further show that lnc-NR2F1 is an evolutionarily conserved lncRNA functionally enhances induced neuronal cell maturation and directly occupies and regulates transcription of neuronal genes including autism-associated genes." (PMID 30628890, 2019). "As a result, NR2F1 is now classified as an ASD gene with “suggestive evidence” in the SFARI (Simons Foundation Autism Research Initiative) database." (PMID 35455940, 2022). "Novel cases are regularly reported and NR2F1 is also recognized as an ASD candidate gene according to the Simons Foundation Autism Research Initiative (SFARI) database." (PMID 35455940, 2022).
glioblastoma (3 papers, 2018 to 2025). The most malignant astrocytic tumor (WHO grade IV). "We note that Nr2f1 has been identified as a master regulator of glioblastoma and part of a core stemness module." (PMID 40864701, 2025). "We found that knock-down of NR2F1-BT and NR2F1 or POU3F3-BT and POU3F3 similarly reduced the invasion/migration potential of U251MG glioblastoma and U2OS osteosarcoma cells." (PMID 29540241, 2018).
melanoma (3 papers, 2018 to 2025). A malignant, usually aggressive tumor composed of atypical, neoplastic melanocytes. "NR2F1 expression could serve as a biomarker to identify patients with melanoma at higher risk of relapse after BRAFi + MEKi therapy, particularly those with invasive or drug-tolerant disease." (PMID 40955667, 2025). "Dormancy and drug tolerance have been linked to resistance and disease relapse in melanoma; therefore, we questioned whether NR2F1 contributes to BRAFi + MEKi tolerance and the persistence of MRD burden." (PMID 40955663, 2025). "Importantly, a positive correlation exists between NR2F1 and genes associated with the “invasive” Wnt5AhiAXLhi signature of melanoma tumors surrounded by an aged TME." (PMID 40955663, 2025). "Here, we show that NR2F1 is highly expressed in melanoma patient samples characteristic of the invasive subgroup of DTPs and in cell-derived xenografts in MRD following treatment with BRAFi + MEKi." (PMID 40955663, 2025). "Altogether, these data suggest that inhibiting mTORC1 with rapamycin treatment improves targeted inhibitor therapy by targeting DTP melanomas that overexpress NR2F1 and decreases regrowth rates of MRD." (PMID 40955663, 2025). "Real-time IncuCyte monitoring of cell growth confirmed the ability of NR2F1-overexpressing cells to maintain growth following a 28-day exposure to BRAFi + MEKi across multiple melanoma lines." (PMID 40955663, 2025). "Our results suggest that targeting NR2F1 in concert with BRAFi + MEKi will likely promote more durable responses to targeted therapy for BRAF-mutant melanoma in vivo." (PMID 40955663, 2025). "Inducible overexpression of NR2F1 reduced BRAFi + MEKi efficacy in melanoma models in vitro and in vivo." (PMID 40955663, 2025). "Using a 3D tumor spheroid outgrowth assay, we found that NR2F1 expression enhanced melanoma invasiveness in spheroids treated with BRAFi + MEKi." (PMID 40955663, 2025). "To investigate how NR2F1 is involved in drug-tolerant persistence, we induced overexpression of NR2F1 in melanoma cell lines." (PMID 40955663, 2025). "A similar elevation of NR2F1 levels in melanoma cells conditioned with skin fibroblasts from older, healthy donors suggested that the aged TME contributed to NR2F1 expression." (PMID 40955667, 2025). "Together, these data suggest that NR2F1 is expressed in the tumors of patients with melanoma with MRD." (PMID 40955663, 2025). "We also examined the expression levels of NR2F1 in aged TME-derived melanomas and showed that knockdown of NR2F1 in tumor-bearing aged mice reduced growth and improved survival following BRAFi + MEKi." (PMID 40955663, 2025). "NR2F1 expression was enhanced in the undifferentiated cell state, 1of 4 melanoma states identified as highly invasive and resistant to BRAFi + MEKi." (PMID 40955663, 2025). "In sum, our data suggest that NR2F1 confers a pro-growth and pro-invasion state in melanoma during targeted therapy." (PMID 40955663, 2025). "Targeting BRAFi + MEKi–tolerant cells that overexpressed NR2F1 using the mTOR inhibitor rapamycin delayed melanoma regrowth and the emergence of resistance." (PMID 40955663, 2025). "Overall, our data indicate that NR2F1 maintained cell growth in drug-tolerant melanoma subjected to targeted therapy, in part, through enhancement of the level of mTORC1 signaling during BRAFi + MEKi treatment." (PMID 40955663, 2025). "Combining BRAFi + MEKi with the mTORC1 inhibitor rapamycin effectively targeted these resistant melanoma cells, suggesting a potential path forward for targeting NR2F1 and mTORC1 signaling in patients with CM." (PMID 40955667, 2025). "Together, these data suggest that BRAF-mutant melanoma cells expressing high levels of NR2F1 tolerate targeted therapy and that tumors develop resistance more quickly." (PMID 40955663, 2025). "Melanomas from aged mice, known to exhibit decreased responses to BRAFi + MEKi, displayed higher levels of NR2F1 compared to tumors from young mice." (PMID 40955663, 2025).
melanoma (continued). "Transcriptomic analysis of melanoma patient samples treated with BRAFi + MEKi showed increased NR2F1." (PMID 40955663, 2025). "Several key unanswered questions and future directions emerge from the study of NR2F1 in melanoma therapy resistance." (PMID 40955667, 2025). "Our finding that NR2F1 was upregulated in melanoma residual tumors from patients and mice on BRAFi + MEKi treatment were consistent with studies that identified dormant marker expression in cells in the MRD state." (PMID 40955663, 2025). "Here, we show that NR2F1 played a role in the survival of drug-tolerant melanoma lesions." (PMID 40955663, 2025). "Considering the potential importance of NR2F1 in regulating tumor latency and melanoma MRD, diving even deeper into mechanism(s) of action will provide additional opportunities to develop creative and potentially effective therapies in treating residual and therapy-refractive disease." (PMID 40955667, 2025). "NR2F1 overexpression is reported to upregulate SOX9 through RAR-β; SOX9 overexpression has been linked to the promotion of migration, metastasis, and resistance to targeted therapy in melanoma." (PMID 40955663, 2025). "Additional studies are warranted to determine how NR2F1 might play a role in the maintenance of drug-tolerant melanoma cells." (PMID 40955663, 2025). "Tiago and colleagues’ analysis of published single-cell and bulk transcriptomics datasets confirmed that NR2F1 was highly expressed in BRAFi + MEKi–treated patients with melanoma and BRAF-mutant melanoma patient–derived xenografts, particularly in invasive MRD, as well as in preclinical cell models." (PMID 40955667, 2025). "Depleting NR2F1 in an aged mouse melanomas improved the response to targeted therapy." (PMID 40955663, 2025). "Together, our findings indicate that targeting DTP cells expressing high levels of NR2F1 may improve targeted therapy outcomes in melanoma." (PMID 40955663, 2025). "Notably, Tiago and colleagues also reported that melanomas in aged mice exhibited elevated NR2F1 levels, aligning with prior observations that aged mice showed a poorer response to BRAFi + MEKi than did their younger counterparts." (PMID 40955667, 2025). "NR2F1 is upregulated in melanoma tumors following BRAFi and MEKi therapy." (PMID 40955663, 2025). "Melanoma cells cultured in conditioned medium (CM) derived from skin fibroblasts isolated from aged healthy human donors (>55 years old) expressed a higher level of NR2F1 compared with cells cultured in young donor (<35 years old) fibroblast–derived CM." (PMID 40955663, 2025). "NR2F1 knockdown in aged melanoma models improved drug efficacy and delayed disease progression." (PMID 40955667, 2025). "Therapeutically, it remains to be determined whether NR2F1 can be directly targeted in melanoma with small-molecule inhibitors or degraders." (PMID 40955667, 2025). "In vitro, both the mTORC1/2i AZD2014 and the mTORC1i rapamycin, inhibited the growth of NR2F1-overexpressing cells, indicating that targeting mTORC1 may delay melanoma relapse." (PMID 40955663, 2025). "Since the majority of patients diagnosed with melanoma are above 66 years of age, and older individuals with melanoma respond worse to BRAFi + MEKi treatment than do younger individuals, we used aged mice to determine whether NR2F1 expression was differentially affected by an aged TME." (PMID 40955663, 2025). "Given the similarities between drug tolerance and cellular dormancy, we studied the dormancy marker, nuclear receptor subfamily 2 group F member 1 (NR2F1), in response to BRAF-V600E inhibitors (BRAFi) plus MEK inhibitors (MEKi) in BRAF-mutant melanoma models." (PMID 40955663, 2025). "Real-time monitoring assays of cell growth over 3 weeks indicated that NR2F1-overexpressing cells responded better to the triple combination treatment, suggesting a potential therapeutic strategy to target DTP melanoma cells." (PMID 40955663, 2025).
melanoma (continued). "BRAF-mutant melanomas that emerged from an aged TME, known to be less sensitive to BRAFi + MEKi, also upregulated NR2F1 protein levels." (PMID 40955663, 2025). "No other members of the NR2F family were upregulated when NR2F1 was overexpressed in melanoma cell lines." (PMID 40955663, 2025). "Studying the dormancy marker, NR2F1, in response to BRAF and MEK inhibitors reveals its role in promoting drug tolerance and highlights the use of mTORC1 inhibitors as a potential strategy for melanoma treatment." (PMID 40955663, 2025). "Together, these data suggest that NR2F1 overexpression affects multiple components of dormancy, but not always consistently between cell lines, in melanoma treated with BRAFi + MEKi." (PMID 40955663, 2025). "The role of NR2F1 in modulating immunotherapy responses also warrants investigation, including whether NR2F1-high melanomas are more responsive to PD-1 or CTLA-4 blockade, or if NR2F1 influences T cell infiltration." (PMID 40955667, 2025). "In colony growth assays, inducible expression of NR2F1 did not alter melanoma cell growth in the absence of BRAFi + MEKi but was able to partially rescue colony growth in the presence of BRAFi + MEKi." (PMID 40955663, 2025). "Future studies are warranted to clarify whether strategies that modulate NR2F1 activity, either through inhibition or agonism, could confer clinical benefit in the context of BRAF-mutant melanoma." (PMID 40955667, 2025). "To confirm that NR2F1 confers a survival benefit to melanoma cells in the presence of BRAFi + MEKi, we inducibly expressed either tdTomato-NR2F1-WT or a dominant-negative form of NR2F1, GFP-NR2F1-C141S, in 1205Lu-TR and WM793TR melanoma cells, which express the Tet repressor (TetR)." (PMID 40955663, 2025). "Combining BRAFi + MEKi with mTOR inhibitors (e.g., rapamycin) suppressed NR2F1-driven MRD and delayed relapse, suggesting that targeting NR2F1 or downstream pathways in DTP cells is a potentially viable strategy to overcome dormancy-like resistance to melanoma therapy." (PMID 40955667, 2025). "In 3 melanoma cell lines (1205Lu, WM793, and A375), NR2F1 expression induced an enrichment in the hallmark gene sets for MYC targets variant 2 and mTORC1 signaling in the presence BRAFi + MEKi compared with treated control cells that did not overexpress NR2F1." (PMID 40955663, 2025). "To determine whether NR2F1 is sufficient to enhance drug tolerance, we induced the expression of NR2F1 in BRAF-V600E 1205Lu, WM793, and A375 melanoma cell lines and treated them with or without BRAFi + MEKi." (PMID 40955663, 2025). "To investigate how NR2F1 may lead to targeted therapy tolerance, we performed bulk RNA-Seq and gene set enrichment analysis (GSEA) on melanoma cells with or without NR2F1 overexpression that were treated with BRAFi + MEKi." (PMID 40955663, 2025).
Parkinson disease (3 papers, 2023 to 2026). A progressive degenerative disorder of the central nervous system characterized by loss of dopamine producing neurons in the substantia nigra and the presence of Lewy bodies in the substantia nigra and locus coeruleus. "Altered NR2F1 expression has also been reported in Down syndrome human-derived neural cells as well as in neurodegenerative disorders, including in mouse models of Alzheimer's and Parkinson's diseases." (PMID 37260288, 2023).
Visual impairment (3 papers, 2019 to 2025). "BBSOAS patients were first identified for their unique combination of cerebral and visual impairments, suggesting that besides cortical development, NR2F1 might also influence the establishment of the visual system." (PMID 34975398, 2021). "The high degree of conservation of Nr2f1 expression between the human and rodent visual pathway allowed the use of the mouse as a model system to study BBSOAS-related visual impairments." (PMID 34975398, 2021).
Waardenburg syndrome type 4 (3 papers, 2016 to 2023). "Here, we report the generation and characterization of a novel mouse model for Waardenburg syndrome type 4, which involves overexpression of the transcription-factor-encoding gene Nr2f1 and its overlapping antisense long noncoding (lnc)RNA A830082K12Rik in NCCs." (PMID 27585883, 2016). "In accordance with these findings, the “Spot” mutation in the Nr2f1-A830082K12Rik gene pair locus stimulates the premature maturation of glial progenitors and leads to the hypopigmentation including in the inner ear, altogether causing a Waardenburg syndrome type 4-like phenotype." (PMID 34274976, 2021). "Taken together, our data thus identify silencer elements of the Nr2f1-A830082K12Rik gene pair as new candidate loci for Waardenburg syndrome type 4." (PMID 27585883, 2016).
bladder cancer (2 papers, 2022 to 2024). "This study is to elucidate the effect of the LINC00663/EBF1/NR2F1 axis on inflammation and angiogenesis in bladder cancer (BC) and related molecular mechanisms." (PMID 39219375, 2024).
bone metastasis (2 papers, 2021 to 2023). Transfer of a neoplasm from its primary site to bones. "Patients with NR2F1-high DTCs had longer bone metastasis-free periods than those with NR2F1-low DTCs." (PMID 34064392, 2021).
brain malformations (2 papers, 2020 to 2024). "Previously published high‐resolution MRI scans have mainly focused on the optic nerve/optic chiasm hypotrophy, resulting in poor characterization of possible brain malformations due to NR2F1 pathogenic variants, despite the high frequency of these patients in being diagnosed with ID." (PMID 32484994, 2020). "Taken together, we introduced six new patients with NR2F1 variants located at the initiation site, in the DBD and LBD, and showing similar clinical and brain malformation defects." (PMID 32484994, 2020). "In addition to NR2F1, other FGF8-responsive genes detected in the DEG analysis are implicated in human brain malformations and/or NDDs." (PMID 39485283, 2024).
cognitive disorder (2 papers, 2020 to 2022). A disease affects cognitive processes. "In this study, we report six novel cases of patients carrying NR2F1 mutations who are affected by ID and other cognitive disorders." (PMID 32484994, 2020). "Hence, BBSOAS autistic features and other cognitive impairments could be influenced by impaired arealization upon human NR2F1 perturbations, but further investigation by fMRI is required to investigate potential areal functional impairments." (PMID 35455940, 2022). "In addition, electrophysiological data revealed impairment of two cellular correlates of learning and memory, long-term potentiation and long-term depression in a Nr2f1 HET mouse model, suggesting that altered synaptic plasticity may also contribute to BBSOAS intellectual impairment." (PMID 35455940, 2022).
glioma (2 papers, 2023 to 2024). A benign or malignant brain and spinal cord tumor that arises from glial cells (astrocytes, oligodendrocytes, ependymal cells). "CircHECTD1-463aa (amino acid), a peptide encoded by hsa_circ_0002301 and downregulated in glioma, attenuates ubiquitination of Nuclear receptor subfamily 2 group F member 1 (NR2F1) and promotes tumor vasculogenic mimicry." (PMID 39090090, 2024). "The endogenous expression of NR2F1 in glioma tissues and cells was first determined." (PMID 37968257, 2023). "We found that NR2F1 was markedly increased in glioma tissues and cells compared to NBT and NHA." (PMID 37968257, 2023).